RNF8 (ring finger protein 8)
Description:
E3 ubiquitin-protein ligase that plays a key role in DNA damage signaling via 2 distinct roles: by mediating the 'Lys-63'-linked ubiquitination of histones H2A and H2AX and promoting the recruitment of DNA repair proteins at double-strand breaks (DSBs) sites, and by catalyzing 'Lys-48'-linked ubiquitination to remove target proteins from DNA damage sites. Following DNA DSBs, it is recruited to the sites of damage by ATM-phosphorylated MDC1 and catalyzes the 'Lys-63'-linked ubiquitination of histones H2A and H2AX, thereby promoting the formation of TP53BP1 and BRCA1 ionizing radiation-induced foci (IRIF). Also controls the recruitment of UIMC1-BRCC3 (RAP80-BRCC36) and PAXIP1/PTIP to DNA damage sites. Promotes the recruitment of NBN to DNA damage sites by catalyzing 'Lys-6'-linked ubiquitination of NBN. Also recruited at DNA interstrand cross-links (ICLs) sites and catalyzes 'Lys-63'-linked ubiquitination of histones H2A and H2AX, leading to recruitment of FAAP20/C1orf86 and Fanconi anemia (FA) complex, followed by interstrand cross-link repair. H2A ubiquitination also mediates the ATM-dependent transcriptional silencing at regions flanking DSBs in cis, a mechanism to avoid collision between transcription and repair intermediates. Promotes the formation of 'Lys-63'-linked polyubiquitin chains via interactions with the specific ubiquitin-conjugating UBE2N/UBC13 and ubiquitinates non-histone substrates such as PCNA. Substrates that are polyubiquitinated at 'Lys-63' are usually not targeted for degradation. Also catalyzes the formation of 'Lys-48'-linked polyubiquitin chains via interaction with the ubiquitin-conjugating UBE2L6/UBCH8, leading to degradation of substrate proteins such as CHEK2, JMJD2A/KDM4A and KU80/XRCC5: it is still unclear how the preference toward 'Lys-48'-versus 'Lys-63'-linked ubiquitination is regulated but it could be due to RNF8 ability to interact with specific E2 specific ligases. For instance, interaction with phosphorylated HERC2 promotes the association between RNF8 and UBE2N/UBC13 and favors the specific formation of 'Lys-63'-linked ubiquitin chains. Promotes non-homologous end joining (NHEJ) by promoting the 'Lys-48'-linked ubiquitination and degradation the of KU80/XRCC5. Following DNA damage, mediates the ubiquitination and degradation of JMJD2A/KDM4A in collaboration with RNF168, leading to unmask H4K20me2 mark and promote the recruitment of TP53BP1 at DNA damage sites. Following DNA damage, mediates the ubiquitination and degradation of POLD4/p12, a subunit of DNA polymerase delta. In the absence of POLD4, DNA polymerase delta complex exhibits higher proofreading activity. In addition to its function in damage signaling, also plays a role in higher-order chromatin structure by mediating extensive chromatin decondensation. Involved in the activation of ATM by promoting histone H2B ubiquitination, which indirectly triggers histone H4 'Lys-16' acetylation (H4K16ac), establishing a chromatin environment that promotes efficient activation of ATM kinase. Required in the testis, where it plays a role in the replacement of histones during spermatogenesis. At uncapped telomeres, promotes the joining of deprotected chromosome ends by inducing H2A ubiquitination and TP53BP1 recruitment, suggesting that it may enhance cancer development by aggravating telomere-induced genome instability in case of telomeric crisis. Promotes the assembly of RAD51 at DNA DSBs in the absence of BRCA1 and TP53BP1 Also involved in class switch recombination in immune system, via its role in regulation of DSBs repair. May be required for proper exit from mitosis after spindle checkpoint activation and may regulate cytokinesis. May play a role in the regulation of RXRA-mediated transcriptional activity. Not involved in RXRA ubiquitination by UBE2E2.
Synonyms: hRNF8; KIAA0646
Tractability: Small molecule: a structure with a bound ligand is known. PROTAC: UniProt records ubiquitination sites on it; ubiquitination databases record sites on it.
Gene: Protein-coding gene on chromosome 6 (37,353,979 to 37,394,734, forward strand). Ensembl gene ENSG00000112130.
Subcellular location: Nucleus; Cytoplasm; Midbody; Chromosome, telomere
Subcellular location (Human Protein Atlas): Nucleoplasm; Cytosol
Pathways (Reactome):
DNA Repair: Nonhomologous End-Joining (NHEJ); Processing of DNA double-strand break ends; Recruitment and ATM-mediated phosphorylation of repair and signaling proteins at DNA double strand breaks
Cell Cycle: G2/M DNA damage checkpoint
Gene Ontology:
Molecular function: chromatin binding; histone binding; identical protein binding; protein binding; protein homodimerization activity; ubiquitin protein ligase activity; ubiquitin protein ligase binding; zinc ion binding; ubiquitin binding; ubiquitin-protein transferase activity
Biological process: DNA damage response; DNA repair-dependent chromatin remodeling; double-strand break repair; epigenetic regulation of gene expression; negative regulation of transcription elongation by RNA polymerase II; positive regulation of DNA repair; positive regulation of double-strand break repair via homologous recombination; protein autoubiquitination; protein K48-linked ubiquitination; protein K6-linked ubiquitination; protein K63-linked ubiquitination; response to ionizing radiation; ubiquitin-dependent protein catabolic process; double-strand break repair via nonhomologous end joining; interstrand cross-link repair; isotype switching; sperm DNA condensation; chromatin organization; protein ubiquitination; signal transduction in response to DNA damage
Cellular component: nucleoplasm; nucleus; site of double-strand break; ubiquitin ligase complex; chromosome, telomeric region; chromosome; cytoplasm; midbody
Genetic constraint (gnomAD): Loss-of-function variants: 6 observed, 53.38 expected, observed/expected ratio (o/e) 0.11, 90% interval 0.061 to 0.22. The synonymous counts are far from expectation, so gnomAD's model fits this gene poorly and the ratio says little. Missense variants: 395 observed, 567.79 expected, observed/expected ratio (o/e) 0.7, 90% interval 0.64 to 0.76. Synonymous variants: 155 observed, 196.75 expected, observed/expected ratio (o/e) 0.79, 90% interval 0.69 to 0.9.
Homologues: Orthologues: chimpanzee RNF8 (99% identical), pig RNF8 (84% identical), guinea pig RNF8 (74% identical), mouse Rnf8 (71% identical), rabbit RNF8 (67% identical), tropical clawed frog rnf8 (47% identical), zebrafish rnf8 (38% identical).
Diseases named in the same sentence as RNF8 in open-access papers:
RNF8 is named in the same sentence as 73 diseases in open-access papers, as found by Europe PMC text mining. Sharing a sentence is not in itself a finding about the gene and the disease. The quoted sentences say what the papers report.
breast carcinoma (21 papers, 2011 to 2025). "In breast cancer, RNF8 is associated with many key clinical parameters such as estrogen receptor status, IHC positive cells, and progesterone receptor." (PMID 35831895, 2022). "miR-622 targets Yes-associated protein (YAP) in glioma and targets ring finger protein 8 (RNF8) in breast cancer." (PMID 35872695, 2022). "We also analyzed the association between RNF8 expression and the clinic pathological parameters in breast cancer." (PMID 27259701, 2016). "Additionally, RNF8 is an associated partner of estrogen receptor α (ERα) and activates ERα-mediated responses in breast cancer cells in vitro." (PMID 33912571, 2021). "Since our results indicated that RNF8 might be a crucial target for miR-622, we also found that some functions of miR-622 targets are associated with breast cancer." (PMID 31709182, 2019). "Furthermore, we proved that these metastatic behavior promoting effects of RNF8 in breast cancer was associated with the inactivation of GSK-3β and activation of β-catenin signaling." (PMID 27259701, 2016). "Taken together, these findings demonstrate that BCKDK‐mediated RNF8 phosphorylation at S157 plays a critical role in tumor progression and contributes to resistance against DNA damage‐inducing therapy in breast cancer." (PMID 40298908, 2025). "By examining DNA damage repair‐associated factors, we observed a large decrease in RAD51 protein levels following BCKDK knockdown, while RAD51 levels increased upon RNF8 knockdown in breast cancer cell lines." (PMID 40298908, 2025). "Specifically, overexpression of hsa-miR-214-3p has been shown to inhibit proliferation and invasion in breast cancer cells and to regulate epithelial-mesenchymal transition through the downregulation of RNF8." (PMID 39735676, 2025). "This study reveals that BCKDK can localize within the nuclei of breast cancer cells, where it binds to and phosphorylates RNF8, thereby inhibiting the ubiquitin‐mediated degradation of RAD51." (PMID 40298908, 2025). "We next examined the role of the BCKDK/p‐RNF8/RAD51 axis in contributing to therapy resistance in breast cancer." (PMID 40298908, 2025). "Western blot analysis revealed that RAD51 ubiquitination levels were increased in BCKDK‐silenced breast cancer cells, an effect that was restored with RNF8 knockdown." (PMID 40298908, 2025). "This study has demonstrated that BCKDK localizes to breast cancer cell nuclei, where it binds to and phosphorylates RNF8, thereby blocking ubiquitin‐mediated degradation of RAD51 and enhancing HRR." (PMID 40298908, 2025). "Previously, we discovered that RNF8 promoted epithelial-mesenchymal transition in breast cancer and lung cancer, which indicated the potential role of RNF8 in cancer metastasis." (PMID 37154586, 2023). "It was reported that RNF8 promotes breast cancer metastasis via enhancing Epithelial-mesenchymal transition (EMT)." (PMID 37007972, 2023). "Another role of RNF8 is to promote lung cancer tumorigenesis and chemoresistance and to promote breast cancer metastasis, similar to a “Villain”." (PMID 35831895, 2022). "Ring finger protein 8 (RNF8), a predicted target hub gene with a high target site accessibility, was recently proven to have a strong relation to breast cancer and lung cancer." (PMID 35742854, 2022). "We are quite curious about how RNF8 regulates abundant and different biological processes such as breast cancer metastasis, lung cancer tumorigenesis, DNA double-strand break repair, chromatin remodeling and spermatogenesis." (PMID 35831895, 2022). "RNF8 was demonstrated to activate Ubc13 and recruit K63-linked poly-ubiquitin conjugation to histones H2A/H2AX, thus contributing to breast cancer predisposition." (PMID 35874839, 2022). "To investigate the contribution of RNF8 to cancer progression in different breast cancer subtypes, we determined RNF8, SNAI1, and CDH1 expression levels in TNBC and non-TNBC breast cancer subtypes using the TCGA RNA-seq dataset." (PMID 34357122, 2021).
breast carcinoma (continued). "Ring finger protein 8 is known as a promising target for chemotherapy because it is aberrantly expressed in many breast cancer patients, promotes tumor metastasis, and plays a key role in the DDR pathway." (PMID 33912571, 2021). "As with the results in vitro, it was confirmed that RNF8 was positively correlated with ERα in breast cancer patient tissues." (PMID 33912571, 2021). "In summary, these results experimentally identified RNF8 as a new target of miR-622 in breast cancer, revealing a new role for miR-622 in breast cancer tumorigenesis and verified our targets and functional analysis of miR-622." (PMID 31709182, 2019). "Subsequently, we demonstrated that miR-622 can regulate the EMT process, cell migration, and cell viability in breast cancer by directly regulating RNF8 expression." (PMID 31709182, 2019). "We designed complete in vitro experiments and validated the regulatory pattern of miR-622-RNF8 in breast cancer EMT process because the relationship between RNF8 and breast cancer metastasis (including EMT) has been demonstrated recently." (PMID 31709182, 2019). "The expression of RNF8 was upregulated in breast cancers when compared with normal adjacent tissues." (PMID 27259701, 2016). "Metastatic nodules in the lungs were found in five of the six control group mice (5/6), but only in one of the six shRNF8 group mice (1/6); these data provided further evidence that RNF8 promotes breast cancer metastasis in vivo." (PMID 27259701, 2016). "Overexpression of RNF8 induces EMT in breast cancer cells, promotes breast cell migration and tumor metastasis in mouse xenograft model." (PMID 27259701, 2016). "Taken together, these results indicate that overexpression of RNF8 induce mesenchymal phenotypes, while depletion of RNF8 induce epithelial-like phenotypes of breast cancer cells, suggesting that RNF8 play an important role in EMT program." (PMID 27259701, 2016). "Since RNF8 is aberrantly expressed in many breast cancer patients and facilitates tumor metastasis, and is a key player in the DDR pathway, it is therefore a promising target for anti-cancer therapy." (PMID 27259701, 2016). "In summary, RNF8 induces EMT in breast cancer cell line, and knock down of RNF8 reduces tumor metastasis in nude mice xenograft model." (PMID 27259701, 2016). "The expression of RNF8 is up-regulated in breast cancers tissues, positively correlates with lymph node metastasis and inversely correlates with survival time of the breast cancer patients." (PMID 27259701, 2016). "Based on the evidence that several players in the ubiquitin-mediated BRCA1-dependent DDR seem to contribute to breast cancer predisposition, RNF8, UBC13 and MMS2 were considered plausible candidate genes for susceptibility to breast cancer." (PMID 21774837, 2011). "The present data suggest that mutations in RNF8, UBC13 and MMS2 genes unlikely make any sizeable contribution to breast cancer predisposition in Northern Finland." (PMID 21774837, 2011). "In the current study, the whole coding region of the RNF8, UBC13 and MMS2 genes was systematically screened for mutations in 123 breast cancer families." (PMID 21774837, 2011). "Moreover, forced expression of RNF8WT or RNF8S157D, but not RNF8S157A, promoted cell viability and colony formation in BCKDK‐overexpressing and endogenous RNF8‐silenced breast cancer cells." (PMID 40298908, 2025). "Notably, aberrant expression of the BCKDK/p‐RNF8/RAD51 axis correlates with breast cancer progression and poor patient survival." (PMID 40298908, 2025). "In addition, the survival rate of breast cancer patients was favorably connected with miR-214 levels and negatively connected with RNF8 levels which is a recently discovered regulator that promotes EMT." (PMID 34299149, 2021). "Besides, RNF8 was also found to co-activate ER alpha target genes and prolong ER alpha half-life in breast cancer cells." (PMID 33777799, 2021).
breast carcinoma (continued). "Recently, RNF8 was reported to participate in breast cancer progression 23-25." (PMID 32549753, 2020). "Because RNF8 can induce the EMT process in breast cancer and miR-622 can directly regulate RNF8 expression, we hypothesized that miR-622 can regulate the EMT process via the regulation of RNF8." (PMID 31709182, 2019). "Two recent articles reported that RNF8 could induce the K63-linked ubiquitination of the transcription factor Twist and promote EMT in breast cancer cells, which leads to breast cancer metastasis." (PMID 31709182, 2019). "We reasonably assume that miR-622 might regulate the EMT process of breast cancer cells via the direct regulation of RNF8." (PMID 31709182, 2019). "In breast cancer, 17 genes, including RNF8, DYRK2, RB1, and TRDMT1, could be used as prognostic biomarkers of breast cancer, indicating that these genes, including RNF8, might have a strong relationship with breast cancer." (PMID 31709182, 2019). "The results showed that the overexpression of miR-622 could downregulate the expression of RNF8 and Snail, a mesenchymal hallmark, indicating that miR-622 inhibited the EMT process in breast cancer cells." (PMID 31709182, 2019). "In addition, we found that RNF8 expression was higher in malignant breast cancer than that of the paired normal breast tissues, and was positively correlated with lymph node metastases and poor survival time." (PMID 27259701, 2016). "Taken together, these data demonstrate that RNF8 promotes cell migration in breast cancer cells." (PMID 27259701, 2016). "High-level amplification of RNF8 in lung cancer and leukaemia cells was revealed by the Cancer Genome Project (Sanger Institute), but the role of RNF8 in tumorigenesis, especially in breast cancer metastasis remains poorly defined." (PMID 27259701, 2016). "RNF8 is overexpressed in highly metastatic breast cancer cell lines." (PMID 27259701, 2016). "Importantly, the expression of RNF8 is up-regulated in breast cancers tissues and is positively correlates with lymph node metastasis, establishing an important role for RNF8 in breast cancer metastasis." (PMID 27259701, 2016). "The high levels of RNF8 and low levels of RNF168 in steady-state untreated MCF-7 breast cancer cells may also explain the inability of RNF8 overexpression or its depletion to modulate FOXM1 expression." (PMID 27526106, 2016). "The entire coding region and splice junctions of RNF8, UBC13 and MMS2 genes were screened for mutations in affected index cases from 123 Northern Finnish breast cancer families by using conformation sensitive gel electrophoresis, high resolution melting (HRM) analysis and direct sequencing." (PMID 21774837, 2011). "However, RNF8 appears to have the opposite effect in tumor progression according to recent studies, because it promoted breast cancer proliferation and metastasis by affecting the Wnt/β-catenin pathway and activating the activity of transcription factors such as Twist and ERα 23-25." (PMID 32549753, 2020). "Also, we suppose that breast cancer metastasis might be regulated by miR-622 via the regulation of RNF8, which requires further supports via in vivo experiments." (PMID 31709182, 2019). "In addition, after proving the regulation of RNF8 expression by miR-622, we believe it is reasonable to assume that the RNF8-induced increase in breast cancer cell migration capacity might be directly regulated by miR-622." (PMID 31709182, 2019). "Furthermore, we found that the overexpression of miR-622 in breast cancer cells can downregulate the expression of RNF8, while miR-622 knockdown by the antagomir could increase the protein level of RNF8, which verified the regulation of RNF8 by miR-622." (PMID 31709182, 2019). "However the role of RNF8 in the pathogenesis of breast cancer is still unclear." (PMID 27259701, 2016).